STAT6 (signal transducer and activator of transcription 6)
Diseases named in the same sentence as STAT6 in open-access papers (continued):
Sharing a sentence is not in itself a finding about the gene and the disease.
ischemic stroke (13 papers, 2019 to 2025). A stroke disorder caused by obstruction of blood flow to the brain, due to thrombotic (local blood clot formation) or embolic (due to a blood clot or other material traveling from another site) event. "The disruption of S100A9 in M/M ameliorates brain injury through the STAT6/PPARγ pathway in ischemic stroke." (PMID 39107960, 2024). "Our current research findings reveal that S100A9‐mediated M/M polarization exacerbates neuroinflammatory injury through the STAT6/PPARγ pathway in ischemic stroke." (PMID 39107960, 2024). "Our data show that 2′-FL reduced the neurological symptoms of ischemic stroke and ROS accumulation in the brain through IL-4/STAT6-dependent M2-type microglial polarization in MCAO mice." (PMID 37372011, 2023). "For example, the IL-4/STAT6 pathway is one of the canonical pathways of hemorrhage clearance in the brain and STAT6 signaling is activated also after the ischemic stroke." (PMID 33925299, 2021). "Moreover, our research has identified that S100A9‐mediated M/M polarization aggravates neuroinflammatory injury via the STAT6/PPARγ pathway in ischemic stroke, providing a new understanding of the molecular mechanisms involved." (PMID 39107960, 2024). "After an ischemic stroke, microglia and macrophages’ STAT6 is activated." (PMID 39649720, 2024). "In turn, Arg1 was found to be necessary for STAT6-induced efferocytosis post-ischemic stroke." (PMID 36994095, 2023). "Whether IL-13 regulates STAT6 signaling in response to ischemic stroke remains to be determined." (PMID 35578342, 2022). "Importantly, according to upstream regulator analysis, PPARγ and STAT6 may play pivotal roles in determining the pro-efferocytic transcriptome of macrophages in the brain 5 days after ischemic stroke." (PMID 33193029, 2020). "A study on the mechanism of signal transducer and activator of transcription 6/arginase 1 (STAT6/Arg1) in ischemic stroke found that microglia not only phagocyte a large number of apoptotic neurons, but also a small number of viable neurons after ischemic stroke." (PMID 33650762, 2021).
meningioma (13 papers, 2018 to 2025). A generally slow growing tumor attached to the dura mater. "SFTs and meningiomas can be challenging to distinguish using magnetic resonance imaging (MRI), but hematoxylin and eosin (H&E) and immunohistochemical (IHC) staining for STAT6 and SSTR2A can reliably distinguish SFTs from meningiomas." (PMID 37546798, 2023). "Another study that examined immunohistochemical STAT6 nuclear staining revealed that of fifty-nine Grade 2 and 3 meningiomas tested, two Grade 3 tumours and one Grade 2 tumour were positive for STAT6, indicating that they also carried the NAB2-STAT6 fusion." (PMID 36882706, 2023). "IHC was performed, and the diagnosis of anaplastic meningioma was obtained, the left frontopolar lesion being STAT6 negative and SSTR2a positive." (PMID 40283561, 2025). "Although ISFTs were confused with meningiomas on imaging, the STAT6 immunostaining is totally negative in meningiomas." (PMID 35712477, 2022). "However, meningiomas typically express epithelial membrane antigen (EMA) positively, while CD34 and STAT6 are negative." (PMID 39175476, 2024).
parasitic infection (13 papers, 2011 to 2024). "A possible mechanism underlying the resistance to this parasitic infection in STAT6−/− mice is increased activation of M1 macrophages, which favors iNOS expression." (PMID 31810203, 2019). "Considering the paucity of available data, what are the roles of CD209, CD28 and STAT6 gene polymorphisms, either individually or in combination, with malaria infection among children, and how are they associated with markers of disease severity (age, anemia and parasitemia)?" (PMID 31979279, 2020). "IL-4 and IL-13 play a critical role in allergic inflammation and parasite infection and act through the STAT6 signaling pathway." (PMID 39502090, 2024). "Other work in mouse macrophages showed that KDM6B can be upregulated by IL-4 in a STAT-6-dependent manner and that it is essential for IL-4 induced polarization in vitro and in response to certain kinds of parasitic infection in vivo." (PMID 28228757, 2017). "Arginase 1 is also induced in classically activated (M1) macrophages in a STAT6 independent manner via the Toll–like receptor 2/MyD88 pathway following parasitic infection." (PMID 22629434, 2012). "Arginase 1 is highly expressed in a “pro-regenerative” subset of macrophages, known as alternatively activated macrophages, in response to parasitic infection via the STAT6 pathway." (PMID 22629434, 2012). "Drugs targeting master JAK/STAT signaling can also be developed to treat parasitic infections or hypersensitivities, including allergic responses, which are either IgE-dominant (controlling STAT3α and STAT6) or IgG4-dominant (controlling STAT1α and STAT6) reactions." (PMID 34948112, 2021). "The heterozygous variant of the STAT6 gene promoter (rs3024974G/A) presented with the most protection against malaria infection (lowest mean age, PCV and parasitemia), possibly implying that the evolution of this gene in the context of malaria infection is still ongoing." (PMID 31979279, 2020). "A study examining regulatory gene variants in Congo showed a disparate response with STAT6 and FOXP3 among malaria-infected children, with the STAT6 promoter variant rs3024944 being associated with uncomplicated malaria, and the FOXP3 SNP rs11091253 being associated with parasitemia." (PMID 31979279, 2020). "Indeed, dominated T helper type 2 responses in parasitic disease increased arginase expression by IL-4 and IL-13 signaling through the transcription factor STAT6." (PMID 21526166, 2011). "In contrast, the absence of STAT6 induced M1 activation and iNOS expression, which helped control parasitic infection but generated increased inflammation and lung pathology." (PMID 31810203, 2019). "For example, recent reports have shown that STAT6 phosphorylation on Tyr641 was induced by viral or parasitic infection independent of IL-4." (PMID 28099521, 2017). "Infected mice deficient in IL-13 or STAT6 did not reduce SFB or IL-17, and exogenous IL-25 replicated the effects of parasite infection in wild type mice." (PMID 26377648, 2015). "Interestingly, infection of STAT6- but not STAT4-knockout mice with this same (Brazil) strain resulted in decreased parasitemia, inflammation, and mortality when compared with wild-type mice." (PMID 32626662, 2020).
airway hyperresponsiveness (12 papers, 2012 to 2026). "When challenged several weeks later with OVA, allergic inflammatory responses, including airway hyperresponsiveness, were reduced in STAT6-IP-treated mice." (PMID 41904701, 2026). "STAT6 knockout mice did not respond to lL-4 and IL-13, failed to produce IgE, and developed airway hyperresponsiveness after allergen exposure." (PMID 32256362, 2020). "Allergic responses in asthmatic mice, including airway hyperresponsiveness, OVA-specific IgE levels, eosinophil infiltration and Th2-related cytokines could not be alleviated by adoptive transfer of STAT6 deficient Treg-of-B (P) cells." (PMID 33584704, 2020).
Arthritis (12 papers, 2016 to 2024). Inflammation of a joint. "Previous studies have linked IL-4 signaling through IL4Rα to activation of STAT6 pathways and protection in inflammatory models of arthritis." (PMID 30849228, 2019). "Functionally, activation of the STAT6 pathway by IL-4/IL-13 plays a critical role in mitigating and resolving immune activation associated with arthritis." (PMID 27273006, 2016). "Osteoclast differentiation, bone loss and cartilage damage were significantly diminished after N. brasiliensis infection but not in the respective mutant mice, suggesting that control of arthritis by the IL-4/IL-13/STAT6 pathway is associated with substantial protection from joint damage." (PMID 27273006, 2016). "Furthermore, it has been shown in mouse models that deficiency of IL-4 and STAT6 can result in significant increase in arthritis severity, and that overexpression of IL-4 may protect from cartilage erosions." (PMID 27942004, 2016). "It modulates chronic inflammatory responses in different forms of arthritis by regulating Foxp3 expression in regulatory T cells and STAT6 in B cells." (PMID 39161423, 2024). "Helminth infection by Nippostrongylus brasiliensis, which robustly induced Th2 cells and accumulated eosinophils, reduced a TNFtg arthritis mice model by IL-4/IL-13-induced STAT6 signaling." (PMID 35163028, 2022). "STAT6 can be activated by IL-4 and IL-13, mainly regulates Th2 differentiation, and inhibits arthritis and inhibits osteoclast differentiation." (PMID 35002715, 2021). "IL-4/IL-13-mediated activation of the STAT6 pathway is also critical to protect bone and cartilage during arthritis." (PMID 27273006, 2016). "At the molecular level, the attenuation of arthritis is dependent on IL-4/IL-13 secretion and STAT6 signalling pathway in haematopoietic cells." (PMID 27273006, 2016). "Although the induction phase of arthritis was comparable, disease partly resolved in the later stages of N. brasiliensis infected 4–13ko and Stat6−/− mice." (PMID 27273006, 2016). "Interestingly, type 2 responses, including an increased number of eosinophils within the joint, were found protective in murine models of arthritis and were mediated by IL-4/IL-13-induced signal transducer and activator of transcription 6 (STAT6) activation." (PMID 34559213, 2022). "This exacerbation of arthritis was suggested to involve STAT6 signaling." (PMID 35163028, 2022). "STAT6 plays an essential effect in the differentiation process of Treg cells and can be activated by IL-4 and IL-13 to induce the polarization of macrophages, which is crucial in alleviating the immune activation of arthritis." (PMID 35002715, 2021). "Stat4 and Stat6 were found involved in osteoclastogenesis and arthritis." (PMID 32216811, 2020). "However, in other mouse models, the IFN-γ/STAT1 pathway has increased and the IL-4/STAT6 pathway decreased the severity of arthritis." (PMID 27942004, 2016). "Indeed, WT=>Stat6−/− and WT=>WT chimeras displayed similar inhibition of arthritis by N. brasiliensis, suggesting that inhibitory effects depend on STAT6-regulated genes in haematopoietic cells." (PMID 27273006, 2016). "Also, in certain mouse models, the IFN-γ/STAT1 pathway mediates protective effects in autoimmune disease and arthritis, and lack of IL-4 and STAT6 suppresses arthritis." (PMID 27942004, 2016). "N. brasiliensis-infected Stat6−/− mice developed comparable SIA than non-infected mice, confirming the dependence of the STAT6 signalling pathway in the mitigation of arthritis." (PMID 27273006, 2016).
ulcerative colitis (12 papers, 2012 to 2025). An inflammatory bowel disease involving the mucosal surface of the large intestine and rectum. "Wu‐Mei‐Wan promotes macrophage M2 polarization by activating the STAT‐6 pathway, thereby alleviating the symptoms of ulcerative colitis." (PMID 41256230, 2025). "Increased p-STAT6 has also been shown in ulcerative colitis (UC) patients and is involved in IL-13-induced colon epithelia dysfunction." (PMID 27533463, 2016). "The human SNP rs3024505, associated with Type 1 Diabetes, Crohn's disease and ulcerative colitis, maps to BRG1, STAT6, and STAT4 binding at +6.3 k in the mouse." (PMID 22336179, 2012). "CHAC1 may participate in the pathogenesis of ulcerative colitis via the miR-214-3p–STAT6 axis, while PML may be regulated by miRNAs with immunomodulatory functions, such as miR-146b-3p." (PMID 41312366, 2025). "MiRNA-31-5p is also elevated in inflamed ulcerative colitis mucosa, where it suppresses the expression of signal transducer and activator of transcription 6 (STAT6), suppressor of cytokine signaling 1 (SOCS1), and eotaxin-3 (CCL26) via downregulating the IL-13 receptor α-1 (IL13Rα-1) gene." (PMID 37559103, 2023). "Epithelial STAT6 has also been shown to be increased in pediatric subjects with ulcerative colitis." (PMID 32410852, 2020). "This study provides initial insights into potential transcription factors involved in the pathogenesis of ulcerative colitis (UC), specifically highlighting FOXP3, STAT6, and hsa-miR-186-5p." (PMID 40729322, 2025).
atherosclerosis (11 papers, 2014 to 2025). A disease characterized by the build-up of fatty material and calcium deposition in the arterial wall resulting in partial or complete occlusion of the arterial lumen. "It then associates with IL-4/STAT6 to stimulate plaque macrophages and inhibit atherosclerosis progression." (PMID 38674885, 2024). "Activation of TNFRSF9 signaling on the macrophage surface modulates the STAT6/PPARδ signaling pathway, which induces the polarization of macrophages in atherosclerosis toward the M2 type." (PMID 40599317, 2025). "The data suggested that the ARCR herb pair attenuated atherosclerosis in ApoE-/- mice by regulating M1/M2 and Th1/Th2 immune balance via activation of the STAT6 signaling pathway." (PMID 35178108, 2022). "The ARCR herb pair regulated blood lipid metabolism and attenuated atherosclerosis in ApoE-/- mice by regulating the M1/M2 and Th1/Th2 immune balance and activating the STAT6 signaling pathway." (PMID 35178108, 2022). "The ARCR herb pair regulates blood lipid metabolism and attenuates atherosclerosis via regulation of M1/M2 and Th1/Th2 immune balance, which is achieved partially by increasing STAT6 phosphorylation." (PMID 35178108, 2022). "We previously reported that atherosclerosis resolution requires recruitment of new Stat6-expressing monocytes to plaques." (PMID 33720008, 2021). "We investigated the roles of the cytokines IL-4 and IL-13, the classical activators of STAT6, in the resolution of atherosclerosis inflammation." (PMID 33720008, 2021). "To begin to understand the factors upstream of STAT6 needed for atherosclerosis resolution, we examined the requirements for the canonical activators of STAT6, namely IL-4 and IL-13." (PMID 33720008, 2021). "Some drugs alleviate the progression of atherosclerosis via activation of STAT6." (PMID 35178108, 2022). "In the present study, we aimed at determining the signals upstream of STAT6 that induce resolution of atherosclerosis and hypothesized that the classical activators of STAT6, IL-4, and/or IL-13 are involved." (PMID 33720008, 2021). "Importantly, we recently showed that STAT6 is necessary for resolution of murine atherosclerosis in a process that also requires monocytes to be recruited to resolving plaques." (PMID 33720008, 2021). "Taken together, ginsenoside Rb1 protected against atherosclerosis by promoting M2 macrophage polarization and limiting intraplaque inflammatory response, which was achieved by increasing the production of IL‐4 and IL‐13 and STAT6 phosphorylation." (PMID 28944992, 2018). "On the other hand, treatments apt to elicit the expansion of MerTK+ and CD163+ cells (e.g., M2c polarizing agents and IL-4/STAT-6 inhibitors) may help against atherosclerosis progression." (PMID 25972766, 2015). "Considering the important role of M1/M2 macrophage and Th1/Th2 cell balance in inflammation and atherosclerosis, we hypothesized that the ARCR herb pair protected against atherosclerosis by regulating the M1/M2 and Th1/Th2 immune balance via activation of the STAT6 signaling pathway." (PMID 35178108, 2022). "To investigate whether these inhibitory effects of the ARCR herb pair on atherosclerosis were exerted via activation of the STAT6 pathway, we designed the second part of the animal experiment, and an ARCR + STAT6 inhibitor (AS1517499) group was established." (PMID 35178108, 2022). "Furthermore, IL15, which mediates its signal through STATs including STAT6, was reduced more during monocyte-to-macrophage differentiation in patients with SLE, especially in those with atherosclerosis." (PMID 25011540, 2014). "Mechanistically, we found that JAK2 and STAT6 were suppressed to a greater degree during monocyte-to-macrophage differentiation in patients with SLE compared with controls, especially among patients with atherosclerosis." (PMID 25011540, 2014).
atherosclerosis (continued). "Many of the genes differentially regulated during monocyte-to-macrophage differentiation (downregulated genes include JAK2, STAT6, TLR8, and TLR2, and upregulated genes include VEGFB, TGFB1, FN1, IL-1R2, SCARB1, MSR1, and CD163) have been previously reported in the pathogenesis of atherosclerosis." (PMID 25011540, 2014). "Besides, KLF4 was found to cooperate with Stat6 to induce an M2 genetic program and inhibit M1 targets via sequestration of coactivators required for NF-κB activation, which suggested KLF4 to be a novel regulator of macrophage polarization and the treatment of atherosclerosis." (PMID 32065217, 2020).
Fibrous Tumor (11 papers, 2013 to 2025). "Solitary fibrous tumors have a haphazard arrangement of spindled to ovoid cells arranged around branching and dilated vasculature within a variably collagenous stroma; desmin is expressed by a subset of cases while STAT6 positivity is typical." (PMID 36579603, 2022).
Insulin resistance (11 papers, 2012 to 2026). Increased resistance towards insulin, that is, diminished effectiveness of insulin in reducing blood glucose levels. "The BSME-treated, maturing, adipocyte-secreted proteins were detected with a decreased protein level of leptin, TNF-α, IL-6 and STAT-6, which are associated with insulin resistance and macrophage recruitment." (PMID 35209178, 2022). "Hepatic STAT5 deficiency exacerbated hyperglycemia and dyslipidemia and liver-specific STAT6 deletion directly mediated hepatic steatosis and insulin resistance." (PMID 41491570, 2026). "We noticed that the BSME decreased the expression levels of insulin resistance and macrophage chemoattractant proteins, such as TNF-α, IL-6, leptin and STAT-6, in maturing-adipocyte-secreted proteins." (PMID 35209178, 2022). "The ZS-Ag-NPs treatment significantly decreased insulin resistance and metabolic inflammation-related LTB4-R, TNF-α, IL-4 and STAT-6 mRNA levels." (PMID 34685001, 2021). "IL-4 influences lipid metabolism via STAT6, promoting adipogenesis, lipolysis, and reducing leptin levels, thereby improving insulin resistance or inducing white adipose browning in the absence of leptin." (PMID 41007770, 2025). "Then, it is reasonable to speculate that IL-13 plays a protective role in insulin resistance by promoting IRS-1 and AKT phosphorylation in insulin-dependent tissues via STAT3 and STAT6 activation as well as improvement of the beta-cell function." (PMID 29675435, 2018). "Furthermore, the analysis of condition media showed the absence of insulin resistance and immune cell-attracting inflammatory markers, such as LTB4, STAT-6, IL-4 and TNF-α levels." (PMID 32235695, 2020).